ANGPTL7 (angiopoietin like 7)
Diseases named in the same sentence as ANGPTL7 in open-access papers (continued):
Sharing a sentence is not in itself a finding about the gene and the disease.
dyslipidemia (2 papers, 2017 to 2023). "In general, our results suggest that increased ANGPTL7 is associated with increasing risk of metabolic syndrome, with the exception of BMI, where increased ANGPTL7 is associated with decreased BMI." (PMID 37550624, 2023). "Physical exercise reduced the level of ANGPTL7 highlighting the potential for targeting this protein as a therapeutic target for regulating dyslipidemia." (PMID 28264047, 2017).
high blood pressure (2 papers, 2014 to 2020). "Previous study showed that ANGPTL7 was highly expressed in patients with hypertension, and downregulation of ANGPTL7 alleviated angiotensin II-induced hypertension and vascular inflammation." (PMID 33313310, 2020). "Currently available researches have shown the role of ANGPTL7 in patients with diabetes, acute heart failure, and hypertension." (PMID 33313310, 2020). "This list included Angptl7, Hdc, Cndp2, Dna2, Edn3, which were up-regulated in the hypertensive mice and may have a physiological role in the regulation of high blood pressure." (PMID 25259444, 2014).
melanoma (2 papers, 2015 to 2021). A malignant, usually aggressive tumor composed of atypical, neoplastic melanocytes. "Whether lymphatic drainage is related to the effect of Angptl7 on melanoma remains to be elucidated." (PMID 34447410, 2021).
open-angle glaucoma (2 papers, 2020 to 2022). Chronic outflow obstruction of the eye's drainage canals that can lead to increased internal eye pressure and optic nerve damage. "Therapeutic knockdown of ANGPTL7 in patients with open angle glaucoma may present a unique opportunity to not only lower IOP through a novel mechanism of action, but also to intervene in the disease process." (PMID 36192519, 2022).
alcohol (1 paper, 2023). "We observe positive colocalization [posterior probability (PP) > 80%] for 5 of 18 proteins with the same traits (ADGRE2 and total cholesterol [TC]; ANGPTL7 and BMI, waist-hip ratio; ITGB7 and TC; NOMO1 and LDL, TC; SEMA3F and BMI, alcohol use), supporting the two-sample MR results." (PMID 37550624, 2023).
breast tumors (1 paper, 2021). "ANGPTL7 expression was significantly higher in 4T1.2 primary breast tumors than 4T1 primary breast tumors (p = 0.0001), suggesting that cells maintained the increased expression of ANGPTL7 when they formed breast tumors in mice." (PMID 34072157, 2021). "Therefore, to validate our RNA-seq data of ANGPTL7, a qPCR analysis was performed using primary breast tumors of 4T1 and 4T1.2 compared with the expression level at the metastatic sites, e.g., spine, bone, and lung using 4T1.2 syngeneic recurrence/metastasis mouse model." (PMID 34072157, 2021).
coronary stenosis (1 paper, 2025). Narrowing of the coronary artery lumen diameter. "Patients with ≥90% coronary stenosis had significantly higher levels of serum ANGPTL7 [1.79(1.13, 2.35) ng/ml] than those with ≤50% stenosis [1.11(0.93, 1.59) ng/ml] with a significantly statistical difference (P < 0.001)." (PMID 41143193, 2025). "In terms of myocardial ischemia-induced angiogenesis after coronary stenosis, the role of ANGPTL7 is still unknown." (PMID 41143193, 2025). "For patients with severe coronary stenosis, participants in the control group and the poor CCC group both had lower serum ANGPTL7 concentrations than the good CCC group." (PMID 41143193, 2025). "In this study, we aim to investigate the role of ANGPTL7 in angiogenesis and evaluate the predictive value of serum ANGPTL7 in CCC formation and the clinical prognosis of CHD patients with severe coronary stenosis (SCS)." (PMID 41143193, 2025).
disc degeneration (1 paper, 2017). "However, the role of ANGPTL7 and Semaphorin 3E in disc degeneration is currently unknown and requires further investigations." (PMID 28358123, 2017).
endothelial dysfunction (1 paper, 2022). In vascular diseases, endothelial dysfunction is a systemic pathological state of the endothelium (the inner lining of blood vessels) and can be broadly defined as an imbalance between vasodilating and vasoconstricting substances produced by (or acting on) the endothelium. "In addition to lipid metabolism, ANGPTL7 also plays a role in oxidative stress, inflammation and cell adhesion through its role in TNF-α-induced endothelial dysfunction." (PMID 36017324, 2022).
hepatocellular carcinoma (1 paper, 2023). A malignant tumor that arises from hepatocytes. "It has been revealed that ANGPTL7 had an excellent performance as a surrogate marker of microvascular invasion on hepatocellular carcinoma." (PMID 37313409, 2023).
myocardial ischemia (1 paper, 2025). A disorder of cardiac function caused by insufficient blood flow to the muscle tissue of the heart. "Additionally, both mouse model experiments and in vitro studies provided further evidence supporting the role of ANGPTL7 in promoting angiogenesis in response to myocardial ischemia following SCS or total occlusion." (PMID 41143193, 2025).
preeclampsia (1 paper, 2021). Preeclampsia is a hypertensive disorder of pregnancy that is characterized by new-onset hypertension with proteinuria presenting after 20 weeks of gestation, and depending on mild or severe forms may initially present with severe headache, visual disturbances, and hyperreflexia. "TFRC was chosen because it gave the highest score for hsa-miR-1270 on TargetScan and ANGPTL7 was selected because it is related to angiogenesis, and thus has an important link to preeclampsia." (PMID 34070163, 2021). "Since we could not detect any differences in the analysis of NOSTRIN hsa-miR-214-5p between preeclampsia vs. control (NOSTRIN: preeclampsia vs. control: 1.8 × 10−6 vs. 1.0 × 10−6; p = 0.07), we analyzed target genes for hsa-miR-1270 (ANGPTL7 and TFRC)." (PMID 34070163, 2021).
Sepsis (1 paper, 2020). Sepsis is defined as life-threatening organ dysfunction caused by a dysregulated host response to infection. "To investigate the associations between ANGPTL7 levels and preterm outcomes, we compared the levels of ANGPTL7 between the affected and nonaffected groups in each complication (including BPD, NEC, IVH, ROP, and sepsis)." (PMID 33313310, 2020).
triple-negative breast carcinoma (1 paper, 2023). An invasive breast carcinoma which is negative for expression of estrogen receptor (ER), progesterone receptor (PR), and human epidermal growth factor receptor 2 (HER2). "For comparison, model J000106527, which had very low necrosis and ANGPTL7 expression was derived from a patient with T4bN0 high-grade triple-negative breast cancer (TNBC)." (PMID 36853945, 2023).
type 2 diabetes (1 paper, 2023). "Increasing levels of ANGPTL7 is associated with a lower age of menopause, BMI, and high-density lipoprotein (HDL); and greater type 2 diabetes and waist hip ratios." (PMID 37550624, 2023). "We find that increased levels of angiopoietin-related protein 7 (ANGPTL7) are associated with decreased age at menopause, decreased HDL, increased risk for type 2 diabetes, and increased waist to hip ratio (corrected for BMI)." (PMID 37550624, 2023).
tumor (17 papers, 2014 to 2025). "ANGPTL7 protein is secreted and localizes to the perinecrotic zone as a tumor-specific factor, with a partial association to the exosomal fraction." (PMID 41573567, 2025). "Functional studies showed that Angptl7 loss normalizes central necrosis, perinecrotic dilated vessels, metastasis, and reduces circulating tumor cell counts to nearly zero." (PMID 36853945, 2023). "The function of ANGPTL7 in the tumor microenvironment (TME) may be complex associated with tumor progression and metastasis." (PMID 34072157, 2021). "Angptl7 was markedly enriched in a perinecrotic distribution in the tumor core and with little expression in the tumor rim." (PMID 36853945, 2023). "Taken together, these data establish that Angptl7, a tumor-specific factor that is specifically expressed in the tumor interior, is necessary for necrosis formation in the tumor core, dissemination of both single and clustered CTCs, and lung metastasis." (PMID 36853945, 2023). "The enrichment for Angptl7 in the tumor core was further confirmed by qPCR, western blot, and ELISA specific for mouse Angptl7." (PMID 36853945, 2023). "Because Angptl7 expression was undetectable in vitro, but highly induced in vivo, knockdown efficiency was confirmed in harvested tumor." (PMID 36853945, 2023). "The top enriched factor from this analysis was angiopoietin-like 7 (Angptl7), enriched 32-fold in tumor vs. host, and over 16-fold in tumor core vs. tumor rim." (PMID 36853945, 2023). "Taken together, these transcriptional studies reveal that Angptl7 regulates large-scale remodeling of the tumor core." (PMID 36853945, 2023). "Angptl7 supports expression of a subprogram of genes expressed in the tumor core that are involved in blood vessel morphogenesis and neutrophil degranulation." (PMID 36853945, 2023). "By performing spatially focused transcriptional profiling, we identified angiopoietin-like 7 (Angptl7) as a tumor-specific factor localized to the perinecrotic zone." (PMID 36853945, 2023). "We demonstrate that necrosis, vascular remodeling, and metastatic dissemination are dependent on a tumor-secreted factor, angiopoietin-like 7 (Angptl7)." (PMID 36853945, 2023). "We found that ANGPTL1, ANGPTL3, ANGPTL4, ANGPTL6, and ANGPTL7 were differentially expressed between tumor and normal tissues." (PMID 35692877, 2022). "ANGPTL7 has been emerging as an important pro-angiogenetic factor involved in inflammation and tumor progression, and metastasis." (PMID 34072157, 2021). "Expression levels of ANGPTL7 were significantly higher in bone, LN than the primary tumor, with a tendency of reduced expression in lung metastasis." (PMID 34072157, 2021). "We had previously shown that myeloid cells suppressed ANGPTL7 expression in cancer cells, leading to decreased tumor cell proliferation, and in keeping with this, S100A8 or S100A9 knockdown did not alter ANGPTL7 mRNA levels." (PMID 27086923, 2016). "Thus, Angptl7 is both regulated by the local microenvironment in the tumor interior and a regulator of further central necrosis and metastatic dissemination." (PMID 36853945, 2023). "Likewise, we observed marked enrichment for tumor-derived rim and host-derived rim gene expression in both core and rim of Angptl7 knockdowns." (PMID 36853945, 2023). "Importantly, our studies revealed a tumor-cell secreted factor angiopoietin like-7 (Angptl7) that regulates formation of necrosis." (PMID 36853945, 2023). "On a molecular level, Angptl7 depletion resolves vascular morphogenetic, hypoxic, and inflammatory changes associated with the tumor core but not gene programs associated with stress, RNA metabolism and nutrient depletion." (PMID 36853945, 2023). "In contrast, the ANGPTL7 expression score for the TCGA-BRCA cohort using a paired comparison of absolute log2 fold change (FC) gene expression values with Welch’s t-test suggested that ANGPTL7 was significantly higher in adjacent normal tissue compared to the tumor (p < 0.00001)." (PMID 34072157, 2021).
tumor (continued). "We also confirmed that nifedipine could increase the expression of ANGPTL7 gene in the tumor and MDA-MB-231 cells when treated with nifedipine for 48h compared with control." (PMID 25436889, 2014). "Conversely, studies indicating antiangiogenic properties of ANGPTL7 relied on the culture medium supernatant from ANGPTL7-overexpressed tumor cells or corneal cell co-cultures, which could be easily interferred by other substances secreted by tumor or corneal stromal cells." (PMID 41143193, 2025). "We applied tumor core and rim gene sets from our initial xenograft deconvolution experiment, evaluated gene set enrichment between conditions, and observed marked depletion of tumor-derived core and host-derived core gene expression in both core and rim of Angptl7 knockdowns." (PMID 36853945, 2023). "ANGPTL3, ANGPTL4, ANGPTL5, ANGPTL7, and ANGPTL8 were significantly hypermethylated in tumor tissues." (PMID 35692877, 2022). "In contrast, the DNA methylation levels of ANGPTL2, ANGPTL7, and ANGPTL8 were significantly positively correlated with tumor grade, and the DNA methylation levels of ANGPTL3, ANGPTL5, and ANGPTL7 were significantly negatively correlated with age." (PMID 35692877, 2022). "The PCR results showed that ALB, ANGPTL7, IL6, and NGB were down-regulated in the BC tumor tissues, and BLOC1S5-TXNDC5 was up-regulated in the BC tumor tissues." (PMID 35962042, 2022). "ANGPTL7, also known as Cornea-derived transcript 6 (CDT6), reduces tumor growth and abnormal blood vessel formation by inducing fibrosis." (PMID 29389861, 2018). "Furthermore, SHROOM4 appears to regulate the tumor microenvironment (TME) through mechanisms such as angiogenesis and cell cycle modulation mediated by ANGPTL7 and PTPN13 in LUAD, thereby influencing cancer progression." (PMID 41573567, 2025). "While depletion of core gene expression was in line with the significant reduction in necrosis observed by H&E, this depletion was not complete, with 23% of tumor derived core genes and 35% of host derived core genes increased in Angptl7-knockdowns." (PMID 36853945, 2023). "Because Angptl7 expression is low in whole tumor lysates, knockdown was confirmed on a protein level by ELISA of tumor interior, and Angptl7 protein expression was significantly reduced in KD1 and KD3 in the tumor interior, where Angptl7 expression is higher than in whole tumor lysates." (PMID 36853945, 2023). "The expression level of ANGPTL5 showed a significant negative correlation with age, ANGPTL5 and ANGPTL7 showed a significant positive correlation with tumor stage, and ANGPTL7 showed a significant negative correlation with tumor grade." (PMID 35692877, 2022). "ADAMTSL4 and ANGPTL7 proteins were significantly overexpressed in adjacent non-tumour tissues compared with tumour tissues." (PMID 33869274, 2021). "However, Angptl7-knockdown does not correct tumor core defects in RNA and nutrient metabolism, indicative of persistent cellular stress in the tumor interior." (PMID 36853945, 2023). "However, suppression of Angptl7 did not increase either total viable area, tumor weight, or tumor volume, indicating that Angptl7 suppression does not promote tumor growth." (PMID 36853945, 2023).
cancer (16 papers, 2016 to 2025). A tumor composed of atypical neoplastic, often pleomorphic cells that invade other tissues. "Existing research findings implicated ANGPTL7 was a mediator of metastatic progression and a potential target for interference with cancer metastases." (PMID 34906147, 2021). "On the other hand, ANGPTL7 has been associated with various cancers potentially through its interaction with the WNT/-beta-catenin signaling pathway." (PMID 28264047, 2017). "ANGPTL7 belongs to a family of secreted angiopoietin-like proteins with reported functions in the regulation of angiogenesis, cancer migration, and invasion." (PMID 33869274, 2021). "Previous studies have shown the biological function of ANGPTL7 in hematopoietic stem and progenitor cells, trabecular meshwork cells, cancer cells, and osteoblasts." (PMID 33313310, 2020). "In theory, polymorphism rs17036508 located in 3’-UTR of angiopoietin-like 7 gene (ANGPTL7), resulting in upregulation of ANGPTL7 by hypoxia in cancer cells, which exerts a pro-angiogenesis effect." (PMID 28977864, 2017). "In the same system, we previously found that monocytes/macrophages suppressed ANGPTL7 expression in cancer cells." (PMID 27086923, 2016). "It was reported that ferroptosis induced by erastin or RSL3 could downregulate ANGPTL7, which might be involved in the onset of ferroptosis in cancer cells." (PMID 34291083, 2021). "However, the role ANGPTL7 played in regulating angiogenesis in cancer was opposite to that in corneal vascularization." (PMID 33313310, 2020). "Interestingly, liver metastases-infiltrating MDSCs induce also the down-regulation of the antiangiogenic factor angiopoietin-like 7 (ANGPTL7) in cancer cells." (PMID 32133298, 2020). "Notably, 10 over-expressed genes (Comp, Mmp3, Adipoq, Angptl7, Fgg, Hp, Mstn, Saa1, Serpina3n, and Cxcl12) are translated into secreted proteins, and therefore, can be further explored as potential cancer cachexia biomarkers." (PMID 31013615, 2019). "ANGPTL7 is one of the least studied members of this family that has been mainly shown to be involved in myeloid cells metastasis and its level was down regulated in cancer cells." (PMID 28264047, 2017). "Angiopoietin-like 7 (ANGPTL7) expression was greatly reduced in the cancer cells." (PMID 27086923, 2016). "Besides, upregulation of ANGPTL7 has been found in cancer cells after myeloid cell depletion, which affected liver metastasis by diminishing cell growth and vascular density, implying that ANGPTL7 could act as a mediator of metastatic progression and as a promising intervention target." (PMID 34026765, 2021). "The results showed that ALOX12, ANGPTL7, DRD4, and MAPK9 remarkably decreased within ESCC samples relative to non-carcinoma samples, whereas SLC38A1 and ZNF419 were highly expressed." (PMID 34291083, 2021). "ANGPTL7 is a member of the ANGPTL protein family that has been shown to play various roles in key pathways such as lipid metabolism, cancer and stem cell." (PMID 28264047, 2017). "One of the possible reasons could be that angiogenesis secretory factors ANGPTL7 and MMP3 are able to promote vascularization by inducing angiogenesis and thereby overexpressed in several cancers." (PMID 34072157, 2021).
cardiovascular disease (3 papers, 2020 to 2025). "There have been relatively few studies on the role of ANGPTL7 in cardiovascular diseases." (PMID 41143193, 2025).
ANGPTL7 also shares sentences with these, for which no sentence is quoted: colon cancer (2 papers); acute kidney injury (1); atherosclerosis (1); bladder cancer (1); Corneal astigmatism (1); esophageal cancer (1); gastric adenocarcinoma (1); Hypertension (1); invasive ductal carcinomas (1); Meier-Gorlin syndrome (1); obstructive sleep apnea (1); prostate carcinoma (1).